INS (insulin)
Diseases named in the same sentence as INS in open-access papers (continued):
Sharing a sentence is not in itself a finding about the gene and the disease.
cerebral edema (26 papers, 2010 to 2025). "Intravenous LD insulin administration has been associated with an increased risk of cerebral edema." (PMID 36994324, 2021). "Insulin loading dose has been linked to increasing the risk of cerebral edema and worsening shock." (PMID 36994324, 2021). "Eleven were excluded: 8 had received insulin and fluids prior to admission, 2 had cerebral edema and 1 child with mild DKA denied consent." (PMID 34719396, 2021). "Of these, 11 were excluded; 8 had received insulin and fluids, 2 had cerebral edema at presentation, and 1 with mild DKA had denied consent." (PMID 31898531, 2020). "Low-dose insulin IV administration is currently the standard of care in patients with DKA so as to reduce the possibility of the development of cerebral edema which accounts for the majority of all DKA-related deaths in children." (PMID 26966489, 2015). "By contrast, our patient lost consciousness during insulin and fluid substitution and subsequently developed cerebral oedema (according to the established criteria)." (PMID 20723227, 2010). "Notably, the low mortality rate among cerebral edema cases suggests subcutaneous insulin is a viable alternative where intravenous pumps are unavailable." (PMID 40037551, 2025). "An insulin bolus is not recommended in paediatric patients, as it increases the risk for cerebral oedema." (PMID 37568965, 2023). "As insulin enters the brain, these effects may - on a local level-contribute to cerebral oedema during DKA." (PMID 20723227, 2010). "The curriculum was designed to allow providers to review fluid and insulin management in pediatric DKA, along with the recognition and management of cerebral edema, a serious complication in pediatric DKA." (PMID 33644303, 2021). "However, factors related to tonicity statistically associated with brain edema during treatment of DKA include decrease in tonicity, large early infusion volumes, very high [Glu] at presentation, rapid decline in [Glu], very low [Na], and administration of large doses of insulin." (PMID 32984372, 2020). "A 10-year old previously healthy boy with DKA became unconscious and apnoeic due to cerebral oedema (confirmed by abnormal EEG and CT-scan) during treatment with intravenous fluids (36 ml/h) and insulin (0.1 units/kg/h)." (PMID 20723227, 2010). "Nevertheless, symptomatic brain edema is seen in 1-5% of DKA cases, and it has been suggested that inappropriate fluid-electrolyte and insulin therapies may lead to brain edema, but controversy continues on this subject." (PMID 33178500, 2020). "Although osmotic injury from aggressive fluid resuscitation or insulin administration in the first hour of therapy has historically been considered a major factor in the development of DKA-related cerebral edema, recent studies have failed to confirm this hypothesis." (PMID 38001976, 2023).
Hypocalcemia (26 papers, 2015 to 2026). An abnormally decreased calcium concentration in the blood. "The low calcium level in blood can cause ketosis and hypocalcemia, while ketosis leads to insulin resistance, thereby raising the risk of other metabolic diseases." (PMID 32680461, 2020). "Heterozygous- (CasrNuf/+) and homozygous-affected (CasrNuf/Nuf) mice were shown to have hypocalcemia in association with impaired glucose tolerance and insulin secretion." (PMID 28575322, 2017). "Ronacaleret treatment rectified the hypocalcemia of heterozygous-affected (CasrNuf/+) mice, and this was associated with an increase in plasma insulin concentrations." (PMID 28575322, 2017). "Moreover, periparturient hypocalcemia is intricately linked to metabolic activities, where diminished calcium levels adversely affect insulin production, thereby reducing glucose delivery to various tissues." (PMID 38846787, 2024). "Similarly, calcium plays a role in insulin secretion from pancreatic β-cells, and hypocalcemia may affect insulin release and increase the risk of metabolic dysfunction." (PMID 40136609, 2025). "Supplementation with vitamin D can improve insulin sensitivity and help mitigate hypocalcemia-related complications." (PMID 40739560, 2025). "Vitamin D, a fat-soluble vitamin, plays a central role in correcting hypocalcemia by promoting calcium absorption and regulating insulin sensitivity." (PMID 40739560, 2025). "Neonatal hypocalcemia was included as an outcome between glyburide and insulin by 3 studies which involved 749 GDM patients." (PMID 31781670, 2019). "Hypocalcemia was observed during fever which can be attributed to requirement of large number of calcium ions for stimulation of insulin secretion in response to glucose." (PMID 27047022, 2015). "Indeed, cows with hypocalcemia (<2.00 mmol/L) had low insulin and high glucose concentrations, which “support the observation that physiological Ca concentration are required for glucose stimulation of insulin secretion”." (PMID 37835703, 2023). "Hypocalcemia could impair insulin signal transduction and decrease the activity of glucose transporter-463,64." (PMID 35058558, 2022). "After treated with Dapagliflozin, blood glucose was lowered thus the calcium uptake caused by increased insulin secretion was prevented so that bone did not need to release calcium to fight against hypocalcemia." (PMID 31781028, 2019). "However, there was no significant statistical difference between the glyburide and insulin groups in terms of neonatal hypocalcemia (OR, 0.53; 95% CI, 0.11 to 2.63; P = 0.43)." (PMID 31781670, 2019). "Hypocalcemia could reduce the secretion of insulin and by doing so; it may increase the accumulations of lipids in the body." (PMID 29029608, 2017). "Our previous work showed that VDD male offspring exhibit impaired glucose-stimulated insulin secretion and reduced β-cell mass, independent of hypocalcemia, suggesting that VDD enhances BAT thermogenesis partly by diminishing insulin-mediated antilipolytic signaling in brown adipocytes." (PMID 40429675, 2025). "In human studies, hypocalcemia in non-diabetic individuals could also impair insulin release, whereas vitamin D supplementation had no beneficial effect on glucose/insulin homeostasis and the impact of Ca intake was not tested in this situation." (PMID 35058558, 2022).
Hyponatremia (26 papers, 2010 to 2026). An abnormally decreased sodium concentration in the blood. "The results indicated a temporal association between initiation of glucose-lowering medication and hospitalization due to hyponatremia, i.e., the risk of severe hyponatremia was higher for drugs newly initiated versus ongoing treatment, especially for insulin and GLP-1 analog use." (PMID 31875925, 2020). "While guidelines recommend dietary sodium restriction to less than 1.5–2.3 g/day, excessively low sodium intake may be associated with hyponatremia as well as impaired glucose metabolism and insulin sensitivity." (PMID 28758978, 2017). "Proposed underlying mechanisms for DM and hyponatremia include altered vasopressin metabolism and the interaction between insulin and vasopressin—both of which function in the renal collecting duct—as well as the reabsorption of more hypotonic fluid due to slower stomach emptying." (PMID 28445418, 2017). "This patient presented with an acute exacerbation of fatigue, nausea/vomiting, severe hyponatremia, reduced insulin requirements, and evidence of hypovolemic shock." (PMID 40416965, 2025). "Cases with symptoms of ghrelin secretion of insulin, of pancreatic polypeptide, of paraneoplastic sensory neuropathy, or of hyponatremia have been described." (PMID 25328753, 2014). "Among them are inadequate dietary intake, malabsorption, increased protein losses, hypermetabolism, insulin resistance, gastrointestinal bleeding, ascites, inflammation/infection, and hyponatremia." (PMID 21234351, 2010). "In contrast, patients with hyponatremia received more amiodarone, heparin, insulin and antibiotics." (PMID 26271263, 2015). "The number of patients receiving amiodarone, heparin, insulin and antibiotics was higher in those developing hyponatremia during hospitalization compared to others without hyponatremia." (PMID 26271263, 2015).
nicotine addiction (26 papers, 2016 to 2025). "Insulin signaling, ubiquitin-mediated proteolysis, nicotine addiction, and RAS/MAPK pathways were dysregulated." (PMID 40565504, 2025). "The most abundant DEGs were identified in the DM vs. NC comparison, with neuroactive ligand-receptor interactions, the synaptic vesicle cycle, nicotine addiction, and insulin secretion as the main biological processes." (PMID 40413074, 2025). "High expression of FN1 enriched in Nicotine addiction, Cocaine addiction, Insulin secretion and Aldosterone−regulated sodium reabsorption." (PMID 38979407, 2024). "GABAergic synapse, insulin secretion, morphine addiction, nicotine addiction, and synaptic vesicle cycle pathways were significantly inhibited, suggesting that immune function was overactivated in the tumor tissues." (PMID 36506527, 2022). "The genes in blue modules were significantly correlated with insulin secretion, retrograde endocannabinoid signaling, neuroactive ligand-receptor interaction, nicotine addiction and GABAergic synapse." (PMID 36344976, 2022). "The parallel cellular and behavioral findings of insulin's mechanism on the type of impulsivity particularly important in nicotine dependence identify insulin manipulation as a novel strategy for smoking cessation." (PMID 29085297, 2017). "The KEGG pathways enriched in CSDS were mainly involved in insulin signaling, cAMP signaling, endocytosis, ubiquitin mediated proteolysis, glutamatergic and GABAergic synapse, regulation of actin cytoskeleton as well as neurological diseases such as nicotine addiction." (PMID 34093668, 2021).
alcoholic fatty liver disease (25 papers, 2010 to 2025). Lipid infiltration of the hepatic parenchymal cells that is due to alcohol abuse. "Intriguingly, SphK2 is likely a metabolically protective factor in the liver, as Sphk2−/− predisposes to non-alcoholic and alcoholic fatty liver diseases, whereas adenoviral overexpression of SphK2 primarily in the liver improves insulin resistance." (PMID 34530846, 2021). "The Insulin signaling pathway and Non − alcoholic fatty liver disease pathway were significantly upregulated." (PMID 41277976, 2025). "Overall, the pooled results from the 26 RCTs (with 1316 participants) indicated that exercise training significantly reduced liver enzymes (i.e., ALT and AST) and insulin in patients with non-alcoholic fatty liver disease." (PMID 37109347, 2023). "In a cross-sectional study of 172 participants with T2DM, the relationship between the glucagon to insulin ratio and the presence of non-alcoholic fatty liver disease was examined." (PMID 37762748, 2023). "The gene expression regulatory pattern was enriched in the non-alcoholic fatty liver disease pathway, insulin signaling pathway, FoxO signaling pathway, and PPAR signaling pathway, accompanied by lipid deposition in the liver." (PMID 37740216, 2023). "Logistic regression modeling was performed to identify the relationship between non-alcoholic fatty liver disease and independent variables, such as metabolic parameters and insulin resistance." (PMID 27166773, 2016). "Ninety four eligible patients who have non-alcoholic fatty liver disease and who are insulin resistant, will be randomised into either a Mediterranean or low fat diet group for a 3 month intervention period." (PMID 26831892, 2016). "Functional analysis revealed that a shift in genes involved in crucial pathways such as insulin signaling and non-alcoholic fatty liver disease pathways may lead to metabolic diseases in the host." (PMID 37840722, 2023). "In the Wistar rat model, maternal obesogenic diet was associated with increased adiposity index, triglycerides, and insulin as well as multiple changes in the liver that are similar to non-alcoholic fatty liver disease in male offspring but not in female offspring." (PMID 33004997, 2020). "Furthermore, a previous study showed that pioglitazone was also effective for alcoholic steatohepatitis in rats without altering insulin sensitivity." (PMID 24669237, 2014).
carotid atherosclerosis (25 papers, 2014 to 2025). A thickening and loss of elasticity of the walls of carotid arteries that occur with formation of atherosclerotic plaques. "For this reason, we also studied its relationship with the presence of carotid atherosclerosis, and other cardiovascular risk determinants such as lipid profile and resistance to insulin action in RA." (PMID 37892031, 2023). "After adjustment for age and gender, previous intake of oral antidiabetics (0.29 [0.13–0.64]), insulin (0.27 [0.12–0.61]) and angiotensin receptor blocker (0.40 [0.19–0.86]), and current smoking (5.98 [1.61–22.1]) were associated with carotid atherosclerosis." (PMID 37817456, 2023). "Strong associations of fasting insulin with a 5-year progression of carotid atherosclerosis (i.e., IMT, plaque presence) have been shown for middle-aged European and Asian persons." (PMID 34746266, 2021). "In this large population-based study of subjects with subclinical carotid atherosclerosis, we observed that higher fasting serum insulin levels were associated with the presence of intraplaque hemorrhage within the carotid atherosclerotic plaque." (PMID 31958313, 2020). "Our data suggested that DPP-4 inhibitors were associated with the regression of carotid atherosclerosis in insulin-treated T2DM patients." (PMID 28250768, 2017). "In conclusion, our data suggested that DPP-4 inhibitors were associated with the regression of carotid atherosclerosis in insulin-treated T2DM patients free of apparent CVD." (PMID 28250768, 2017). "We hypothesize that this difference may be attributed to the role of genetic polymorphisms in the development of subclinical carotid atherosclerosis in men and the beneficial effects of endogenous estrogen on insulin sensitivity and lipid metabolism in women." (PMID 39479392, 2024). "After univariate analysis, the factors associated with carotid atherosclerosis were age ≥70 years (3.28 [1.18–10, 62]), previous intake of oral antidiabetics (0.33 [0.14–0.73]), insulin (0.28 [0.11–0.66]) and angiotensin receptor blocker (0.45 [0.20–0.98]), and current smoking (5.93 [1.64–32.6])." (PMID 37817456, 2023). "The purpose of this study was to investigate whether insulin therapy in T2DM patients is linked with the increased risk of carotid atherosclerosis in real-world settings." (PMID 33598483, 2021). "The TyG index was also significantly correlated with insulin-stimulated glucose uptake measured as the steady-state plasma glucose concentration during insulin suppression testing, and was better associated with carotid atherosclerosis than HOMA-IR." (PMID 24587359, 2014). "Baseline insulin and glucose levels predict the 5-year progression of subclinical carotid atherosclerosis." (PMID 41527607, 2025). "Multivariable analysis was made to analyze the relationship between MHR and RA disease and features subclinical carotid atherosclerosis, and traditional CV factors including insulin resistance and beta cell function indices." (PMID 37895377, 2023). "After adjustment according to age and gender, previous use of oral antidiabetics and insulin were protective factors for carotid atherosclerosis." (PMID 37817456, 2023). "A multivariable analysis was performed to analyze the relation of IL-1ra to subclinical carotid atherosclerosis, and to traditional CV factors including a complete lipid molecules profile and insulin resistance or beta cell function indices." (PMID 35953706, 2022). "Based on previous research, TyG predicting mortality chiefly in < 65-year groups, a stronger inverse link between insulin sensitivity and carotid atherosclerosis progression in younger/middle-aged men; and METS-IR predicting mortality predominantly in non-elderly adults." (PMID 41458555, 2025).
carotid atherosclerosis (continued). "In univariate analysis, the factors associated with carotid atherosclerosis were the age ≥70 years (OR 3.28 [1,18–10.62]), T2DM newly diagnosed (OR 0.36 [0.14–0.88]), previous use of oral antidiabetics (OR 0.33 [0.14–0.73]) and insulin (OR 0.28 [0.11–0.66])." (PMID 37817456, 2023). "In contrast to these studies, our findings clearly indicate how markers of insulin metabolism are associated with carotid atherosclerosis, and we found this association to be independent of adiposity." (PMID 30470212, 2018). "This diet has been encouraged because of its relationship with an improved cardiovascular profile, including its favorable effect on blood pressure, insulin sensitivity, lipid profiles, lipoprotein particles, oxidative stress, carotid atherosclerosis and inflammation." (PMID 28076613, 2017). "Since adiponectin has insulin-sensitizing, anti-inflammatory and anti-atherogenic properties, low plasma levels of adiponectin can be therefore independent predictors of IHD, and platelet activation in carotid atherosclerosis both in diabetic and non-diabetic subjects." (PMID 30832662, 2019).
chronic myeloid leukemia (25 papers, 2011 to 2025). "KEGG pathways were primarily linked to Neuroactive ligand-receptor interaction (ecb04080), Motor proteins (ecb04814), Insulin signaling pathway (ecb04910), and Chronic myeloid leukemia (ecb05220)." (PMID 40805113, 2025). "In a clinical observation of seven diabetic chronic myeloid leukaemia patients being treated with imatinib, six patients showed improvement in fasting blood glucose concentration which led to a reduction of their insulin dosage or oral antidiabetic drugs." (PMID 38362147, 2024). "A case report of a 57-year-old diabetic chronic myeloid leukaemia patient had their insulin requirements declined upon the introduction of dasatinib." (PMID 38362147, 2024). "KEGG pathway analysis demonstrated that DE mRNAs in the lncRNA-miRNA-mRNA networks mostly enriched in neurotrophin signaling pathway, apoptosis, chronic myeloid leukemia, insulin signaling pathway, platelet activation pathways according to the P<0.05." (PMID 33961683, 2021). "Pathways involved in cell growth, movement and multiplication, such as focal adhesion, MAPK signaling, insulin signaling, chronic myeloid leukemia and TGF-beta signaling were significantly enriched in the differentially-expressed microRNAs in this study." (PMID 24586438, 2014). "The results revealed eight main pathway categories: ERBB signaling, endocytosis, JAK-STAT signaling, T cell receptor signaling, regulation of actin cytoskeleton, insulin signaling, bacterial invasion of epithelial cells and chronic myeloid leukemia." (PMID 24465897, 2014). "As for KEGG, we obtained 58 terms, including “insulin signaling pathway,” “cAMP signaling pathway,” “insulin resistance,” “chemokine signaling pathway,” “chronic myeloid leukemia,” “adrenergic signaling in cardiomyocytes,” and “TNF signaling pathway” in the top 30 terms." (PMID 35935642, 2022). "Target mRNA analysis and subsequent pathway analysis have indicated targets in insulin signalling, MAPK kinase and chronic myeloid leukaemia pathways." (PMID 40301926, 2025). "The top five most activated Kyoto Encyclopedia of Genes and Genomes (KEGG) terms involving ITGB1 were insulin signaling pathway, ERBB signaling pathway, regulation of actin cytoskeleton, chronic myeloid leukemia, and neurotrophin signaling pathway." (PMID 37449209, 2023). "The EN2 variant interacts with components of several archetypal kinase signaling events: ERBB, insulin, JAK and BCR-ABL (chronic myeloid leukemia) based on KEGG enrichment analysis, which also share downstream signaling with ERK/ELK and PI3K/AKT signaling and also with JNK/AP-1 and STAT." (PMID 37686522, 2023).